MGLL (monoglyceride lipase)
Diseases named in the same sentence as MGLL in open-access papers (continued):
Sharing a sentence is not in itself a finding about the gene and the disease.
tumor (104 papers, 2010 to 2026). "Proinflammatory CD80, anti‐inflammatory CD206, CCL18, and CCL22, and the tumor‐associated markers including MMPs, MGLL, and TLR4 were expressed by a low proportion of monocytes (<1%), but significantly upregulated in TAM." (PMID 38037545, 2023). "Conversely, downregulated MGLL contributed to the functional suppression of CD8+ T cells associated with tumor progression." (PMID 36131916, 2022). "In addition, elevated MGLL expression was found to be associated with advanced tumor progression and poor prognosis in LUAD patients." (PMID 33363004, 2020). "Notably, MGLL overexpression (p = 0.0007) still strongly indicated poorer OS, which was also significantly associated with increased tumor size and mitosis and higher GIST risk defined by both the NCCN and NIH schemes (all p < 0.0001)." (PMID 27366945, 2016). "Compared with normal tissues, MGLL mRNA abundance was significantly higher in the GISTs in whole sections (p = 0.001) and increased from normal tissues over the non-high-risk group (p = 0.030) to the high-risk group (p = 0.012), confirming the promotional role of MGLL in tumor progression." (PMID 27366945, 2016). "Conversely, MGLL expression is upregulated in breast and prostate cancers, facilitating tumor progression." (PMID 41345744, 2025). "These consistently high AUC values (> 0.9) across multiple datasets suggest that MGLL expression exhibits significant potential as a biomarker for distinguishing tumor from non-tumor tissues." (PMID 40994935, 2025). "It has been shown that the overexpression of MGLL promotes tumor migration, invasion and proliferation." (PMID 40075699, 2025). "Tumor‐associated marker expression was significantly different among all cell types for MMP2, MMP7, MMP9, MMP12, ABHD5, ADAMTS1, AP‐1, and MGLL each with p < 0.001." (PMID 38037545, 2023). "Monoacylglycerol lipase (MGLL) can lead to lipid overload in TAMs, which functionally inhibits CB-2 cannabinoid receptor-dependent tumour progression in inoculated and genetic cancer models." (PMID 37491279, 2023). "Proinflammatory CD80, CXCL10, anti‐inflammatory IL‐10, and the tumor‐associated markers MMP2, MMP7, MMP12, and MGLL showed lower baseline expression and were upregulated in macrophages as well." (PMID 38037545, 2023). "MGLL is a metabolic enzyme that transforms triglycerides into free fatty acids and is involved in tumor signaling." (PMID 37033945, 2023). "Upregulation of MGLL, a key enzyme in lipid metabolism that also has both tumor promoting and suppressing effects, was most evident in both M0 phenotypes compared to THP‐1 monocytes, but also significant in M2‐like macrophages." (PMID 38037545, 2023). "Mechanistically, MGLL deficiency promotes CB-2/TLR4-dependent macrophage activation, which further suppresses the function of tumour-associated CD8+ T cells." (PMID 37491279, 2023). "According to a study on TNBC suggested that inhibiting MGLL can suppress inflammation, tumor growth, and brain colonization." (PMID 37033945, 2023). "It has been confirmed in the literature that the expression of MGLL in the primary lesion is higher in deeper areas of the tumor, indicating that tumor cells overexpressing MGLL are more aggressive." (PMID 36550099, 2022). "TAMs stimulated and isolated from different mouse tumor models exhibited a reduction in monoacylglycerol lipase (MGLL) expression." (PMID 36131916, 2022). "Accumulating evidence suggests that MGLL promotes tumor invasion and metastasis by up-regulating tumorigenic signals." (PMID 36550099, 2022). "GSEA enrichment analysis showed that overexpression of MGLL resulted in the development of hypoxia in the tumor microenvironment." (PMID 36550099, 2022). "Thereby, the TAM phenotype requires a reduced MGLL expression to stabilize and display immunosuppressive and tumor promoter functions." (PMID 34476174, 2021). "MGLL plays a negative regulatory role in phosphatidylinositol-3 kinase/Akt signaling and tumor cell growth." (PMID 32998690, 2020).
tumor (continued). "MGLL suppressed colony formation in tumor cell lines and knockdown of MGLL resulted in increased Akt phosphorylation." (PMID 32998690, 2020). "We found that the expression of MGLL is higher in LUAD samples than that in adjacent non-tumor tissues." (PMID 33363004, 2020). "We therefore measured the expression of MMP14 in LUAD tissues and found that this protein is upregulated in LUAD relative to non-tumor tissues, and like MGLL, its expression is significantly correlated with overall survival." (PMID 33363004, 2020). "In this study, we present both clinical and experimental evidence demonstrating that MGLL is an oncogenic factor that promotes LUAD tumor cell proliferation and metastasis." (PMID 33363004, 2020). "Consistently, the transgene of MGLL in macrophages largely prolonged the survival of MC-38 tumor-bearing mice." (PMID 29968710, 2018). "Mechanistically, MGLL deficiency promotes CB2/TLR4-dependent macrophage activation, which further suppresses the function of tumor-associated CD8+ T cells." (PMID 29968710, 2018). "In the pathological observation of lung metastasis, we also demonstrated that the macrophage CB2 transgene largely rescued MGLL transgene-reduced tumor lesions." (PMID 29968710, 2018). "Here the authors show that downregulation of monoacylglycerols lipase MGLL in TAMs induces lipid accumulation and tumor progression by polarizing TAMs toward tumor-promoting through activation of cannabinoid receptor CB2." (PMID 29968710, 2018). "To confirm the role of macrophage MGLL in tumor progression, we set up a conditional knockout mouse model with MGLL deficiency in myeloid cells (Myeloid-mgll-KO)." (PMID 29968710, 2018). "Consistently, the MGLL transgene-mediated tumor suppression (tumor volume and survival) was reversed by the addition of a CB2 transgene." (PMID 29968710, 2018). "Furthermore, the study explored the relationship between MGLL expression, tumor immune infiltration, and m7G methylation modifications." (PMID 40994935, 2025). "Through the integration of clinical data, functional clustering analysis, and gene correlation studies, we aimed to establish a comprehensive understanding of MGLL’s impact on tumor behavior and patient survival outcomes, potentially informing novel therapeutic strategies targeting this molecule." (PMID 40994935, 2025). "Notably, downregulation of monoacylglycerol lipase (MGLL) in TAMs supports tumor growth by altering the catabolism of 2-arachidonoylglycerol (2-AG), which activates cannabinoid receptor-2 (CB-2) and promotes M2 macrophage polarization." (PMID 40092297, 2025). "MGLL is typically downregulated in colorectal and liver cancers, functioning as a tumor suppressor." (PMID 41345744, 2025). "Similarly, we discovered that MGLL was abundantly expressed in UM cells, which prompted a phenotypic shift in macrophages to a pro-tumor M2 state." (PMID 37033945, 2023). "Through in vitro and in vivo experiments, we demonstrated that overexpression of MGLL promoted tumor proliferation, metastasis and the occurrence of progestogen resistance, knockdown MGLL inhibited tumor proliferation, metastasis and reversed progestogen resistance." (PMID 36550099, 2022). "Subsequently, we overexpressed and knocked down MGLL in EAC cell lines, respectively and conducted functional experiments in vivo and in vitro.We verified that MGLL could promote the proliferation and inhibit apoptosis of tumor cells." (PMID 36550099, 2022). "Recent studies have found that reduced expression of monoacylglycerol lipase (MGLL) in TAMs facilitates tumor growth and that this molecule can catabolize 2-arachidonoylglycerol (2-AG), which promotes the cannabinoid receptor-2 (CB-2), leading to M2-type polarization of macrophages." (PMID 35454171, 2022). "Furthermore, MGLL downregulation contributes to the suppression of tumor-associated CD8+ T-cell function and tumor progression." (PMID 34476174, 2021). "MGLL has been identified as a unique tumor suppressor for HCC." (PMID 33505467, 2021).
tumor (continued). "Functional studies further demonstrated that stable short hairpin RNA (shRNA)-mediated knockdown of MGLL inhibits tumor proliferation and metastasis, both in vitro and in vivo, and mechanistically, our data indicate that MGLL regulates Cyclin D1 and Cyclin B1 in LUAD cells." (PMID 33363004, 2020). "MGLL knock-out mice exhibited a higher incidence of neoplasia in lung." (PMID 32998690, 2020). "However, we found that MGLL expression in TAMs was reduced and that TAM MGLL functioned as a tumor suppressor." (PMID 29968710, 2018). "We demonstrated that MC-38 tumor-suppressed MGLL mRNA level could be fully rescued by macrophage TgMGLL." (PMID 29968710, 2018). "Notably, MGLL exhibits both upregulation and downregulation patterns across different tumor types, potentially reflecting tissue-specific adaptations, metabolic or microenvironmental influences, gene functional pleiotropy, epigenetic modifications, or transcriptional regulatory mechanisms." (PMID 40994935, 2025). "Thus, MGLL expression and tumor purity should be assessed in tumor samples." (PMID 37033945, 2023). "Furthermore, MGLL overexpression was more frequent in GISTs characterized by the nongastric location, increased tumor size and mitosis, and higher risk levels defined using both the NIH and NCCN schemes." (PMID 27366945, 2016). "Given the novel discovery of the involvement of MGLL-driven lipolysis in promoting carcinogenesis through the modulation of the fatty acid network, we further validated the clinical relevance and prognostic implication of MGLL in cell lines and two independent tumor cohorts." (PMID 27366945, 2016). "Targeted inhibition of monoglyceride lipase (MGLL) affects lipid metabolism and tumor microenvironment." (PMID 41281744, 2025). "We also constructed a prognostic risk model using the four LMRGs signatures, including ENPP2, MGLL, PLCD1, and SLC44A3, and we found that most of them were correlated with tumor progression." (PMID 37033945, 2023). "The group synthesized a nanoplatform that simultaneously delivered MGLL siRNA and CB-2 siRNA to inhibit free fatty acid production in the TME and reprogramme TAMs to polarize into a tumour-inhibiting M1-like TAMs." (PMID 37491279, 2023). "Tumor cells in hypoxia microenvironment can escape drugs targeted at cell division by producing ROS and lead the resistance.So we further examined the effect of MGLL on ROS generation and found that MGLL overexpression could lead to increased generation of ROS in EAC cells." (PMID 36550099, 2022). "Monoacylglycerol lipase (MGLL), a key enzyme in lipid metabolism, has emerged as an important regulator of tumor progression." (PMID 33363004, 2020). "Our data further suggest that MGLL is mainly localized to the cytoplasm in both LUAD and non-tumor tissues." (PMID 33363004, 2020). "Here, to address this question, we measured and compared MGLL expression in LUAD samples and adjacent non-tumor tissues." (PMID 33363004, 2020). "Among the DE genes involved in inflammatory response, solely one gene (AOX1) was found to be upregulated in all four cell types while MGLL was the only gene upregulated in the immortalized keratinocytes and HPV+ tumor cells." (PMID 23702334, 2013). "In addition, the low expression of MGLL is related with poor overall survival of HCC and considered a tumor suppressor in HCC." (PMID 35178443, 2022). "In addition, we detected a positive correlation between expression of MGLL and MMP14 in the 76 tumor tissue samples (P = 0.036)." (PMID 33363004, 2020). "MGLL can inhibit CB2 cannabinoid receptor-dependent tumor progression, and CB2 antagonist treatment can delay tumor progression in mice, which indicates that TLR4 activation can also inhibit tumor growth." (PMID 33224886, 2020). "Therefore, the expression of MGLL and CB2 in TAMs was independently regulated by the tumor microenvironment." (PMID 29968710, 2018).
tumor (continued). "In addition to providing energy, fatty acid metabolism in macrophages can promote immune escape by upregulating tumor cell metabolism through regulatory factors, including those containing ABHD5, monoglyceride lipase (MGLL), and acyl-coenzyme A dehydrogenase medium chain (ACADM)." (PMID 40696413, 2025). "However, it has been found that the expression of macrophage monoacylglycerol lipase (MGLL) in tumor tissues is reduced, and the lack of monoacylglycerol lipase (MGLL) in TAM can lead to triglyceride lipid overload." (PMID 33224886, 2020). "We then conducted western blot analysis to measure MGLL levels in seven pairs of randomly selected LUAD and non-tumor samples, and our data confirm that most tumor tissues display elevated MGLL expression, as compared to adjacent non-tumor tissues." (PMID 33363004, 2020). "Mechanistically, the cannabinoid receptor CB2 can interact with TLR4 and inhibit the pro-inflammatory signaling of TLR4, while lack of MGLL promotes CB2/TLR4-dependent the M2 phenotype in TAMs, thereby inhibiting the function of tumor-related CD8+ T cells and promoting tumor progression." (PMID 33224886, 2020). "However, whether MGLL/CB2 axis in other myeloid cells (dendritic cells, monocytes, etc.)would regulate tumor development is still not elucidated." (PMID 29968710, 2018).
neurological disorders (10 papers, 2017 to 2025). "Rare genetic variants in the core endocannabinoid system genes CNR1, CNR2, DAGLA, MGLL and FAAH were identified in molecular testing data from 6,032 patients with a broad spectrum of neurological disorders." (PMID 29145497, 2017). "It should also be noted that rare genetic variations in ECS, including the genes CNR1 and CNR2 encoding CB1R and CB2R, respectively, as well as the genes for the degrading enzymes DAGLA, MGLL, and FAAH have been reported in patients with neurological disorders." (PMID 39796008, 2024).
metabolic disorders (4 papers, 2021 to 2025). "MGLL, a serine hydrolase primarily expressed in the liver, brain, adipose tissue, and other organs, is implicated in various metabolic disorders, inflammation, and fibrosis." (PMID 40245985, 2025). "Our findings demonstrate that the beneficial effects of AKBA on metabolic disorders are largely dependent on its direct interaction with monoacylglycerol lipase (MGLL) in hepatocytes." (PMID 40245985, 2025). "In conclusion, our study identifies AKBA as a novel and potent MGLL inhibitor and suggests that it holds promise as a therapeutic candidate for NAFLD and related metabolic diseases." (PMID 40245985, 2025). "Similarly, monoglyceride lipase (MGLL) knockout mice display improved glucose tolerance and differential microbial responses to HFD, identifying MGLL as a potential metabolic disease target." (PMID 39791180, 2025).
infection (2 papers, 2016). The state of being infected such as from the introduction of a foreign agent such as serum, vaccine, antigenic substance or organism. "MGLL is involved in Prostaglandin E2 (PGE2) production in response to inflammation and infection which leads to fever." (PMID 27561985, 2016). "In epiphytic material, expression of the control gene MGLL increased at 16 h post‐inoculation (hpi) and then decreased by 48 hpi without returning to pre‐infection levels of expression." (PMID 26238194, 2016).
MGLL also shares sentences with these, for which no sentence is quoted: Anxiety (33 papers); neurodegenerative disease (19); Alzheimer disease (18); Cognitive impairment (12); depression (11); migraine (11); ovarian carcinoma (10); Parkinson’s (9); memory impairment (8); colitis (7); liver fibrosis (6); schizophrenia (6); epilepsy (5); Headache (5); multiple sclerosis (5); atherosclerosis (3); bone cancer (3); breast tumor (3); endometrial cancer (3); inflammatory bowel disease (3); metabolic syndrome (3); neuropathy (3); non-small cell lung carcinoma (3); osteosarcoma (3); pancreatitis (3); psoriasis (3); acute myeloid leukemia (2); brain disease (2); brain injury (2); cognitive decline (2).
A further 100 diseases each share a sentence with MGLL in 2 papers or fewer.